KCNQ5 (potassium voltage-gated channel subfamily Q member 5)
Diseases named in the same sentence as KCNQ5 in open-access papers (continued):
Sharing a sentence is not in itself a finding about the gene and the disease.
head and neck cancer (1 paper, 2022). A primary or metastatic malignant neoplasm affecting the head and neck. "KCNQ5 interacts with celecoxib and is a promising drug for prevention/treatment of several cancers, such as colon, breast, prostate, and head and neck cancers." (PMID 35664298, 2022).
hidradenitis suppurativa (1 paper, 2025). A chronic suppurative and cicatricial disease of the apocrine glands occurring chiefly in the axillae in women and in the groin and anal regions in men. "Potassium channels: Pain perception in hidradenitis suppurativa may be significantly influenced by the dysregulation of potassium channels, including genes such as KCNMA1, KCNQ5, KCNB2, KCND2, KCND3, and KCNAB3, all of which were identified in this study." (PMID 39940809, 2025).
irritable bowel syndrome (1 paper, 2014). Irritable bowel syndrome (IBS) is a chronic functional condition of the lower gastrointestinal (GI) tract characterized by abdominal pain or discomfort and disordered bowel habit (diarrhea, constipation, or fluctuation between the two). "Recent studies showed that KCNQ4 and KCNQ5 genes encode members of the M channel expressed in gastrointestinal smooth muscle and suggested that these genes are associated with irritable bowel syndrome and similar peristalsis diseases." (PMID 25127363, 2014). "Recent studies showed that the KCNQ4 and KCNQ5 genes encode components of the M channel expressed in gastrointestinal smooth muscles and suggested that these genes are associated with irritable bowel syndrome and similar peristalsis diseases." (PMID 25127363, 2014).
muscular dystrophy (1 paper, 2023). Muscular dystrophy (MD) refers to a group of more than 30 genetic diseases characterized by progressive weakness and degeneration of the skeletal muscles that control movement. "Our study opens up new possibilities for the treatment of systemic hypotension in muscular dystrophy patients with pharmacological inhibition of KCNQ5." (PMID 36980233, 2023).
cancer (16 papers, 2011 to 2025). A tumor composed of atypical neoplastic, often pleomorphic cells that invade other tissues. "Another genome-wide association study reported that rs9351963 in KCNQ5 might act as a predictor for diarrhea in irinotecan-treated cancer patients." (PMID 38807370, 2024). "Therefore, polymorphisms of KCNQ5 genes possibly effect incidence of diarrhea as interindividual variation in the drug response among cancer patients treated with irinotecan chemotherapy." (PMID 25127363, 2014). "Several studies have proposed the use of KCNQ5 gene for the early clinical detection of colorectal precancerous lesions and cancer." (PMID 36012492, 2022). "Cellular metabolism and transportation related genes (ALDOA, SLC16A3, TPI1, LDHB, KCNQ5, and PGM1), which are implicated in human cancer, also remained upregulated even 2-month after radiation exposure." (PMID 23216862, 2012). "Although a CLIP4 signal in plasma suggests the presence of tumor DNA when corroborated by KCNQ5 or C9orf50, the suboptimal performance of CLIP4 in gastric and GEJ cancers should be noted." (PMID 39369091, 2025). "The exact role of KCNQ5 in SCA cancer tumor genesis and progression is not known." (PMID 35664298, 2022).
tumor (13 papers, 2011 to 2025). "A tumor-agnostic strategy was applied to detect ctDNA using a multiplex ddPCR assay targeting the DNA methylation markers C9orf50, KCNQ5, and CLIP4." (PMID 39369091, 2025). "In our previous studies, we have demonstrated a high sensitivity of ctDNA detection using the TriMeth test, a tumor-agnostic multiplex droplet digital PCR assay targeting the gastrointestinal cancer-specific DNA methylation markers, C9orf50, KCNQ5, and CLIP4." (PMID 39369091, 2025). "Out of the four CBS hotspots we examined, three of them were associated with nominally significant expression changes of neighboring genes (CENPQ, KCNQ5, and SPG20), and these associations were validated in an independent tumor cohort." (PMID 29670109, 2018). "Additionally, voltage-gated ion channels and genes like KCNQ5, KCNV1, ADAMTS14, MPPED1, and SLC24A2 are linked to tumor traits in these tumors." (PMID 39139281, 2024).
neurological disorders (1 paper, 2022). "Heterozygous gain- and loss-of-function variants in KCNQ5 cause pediatric neurological disorders of different severities." (PMID 36077086, 2022).
KCNQ5 also shares sentences with these, for which no sentence is quoted: breast carcinoma (4 papers); osteosarcoma (3); age-related hearing impairment (2); autism (2); developmental and epileptic encephalopathy (2); developmental delay (2); long QT syndrome (2); lung carcinoma (2); major depression (2); migraine (2); Parkinson disease (2); Ventricular arrhythmia (2); allergic reaction (1); amyotrophic lateral sclerosis (1); angina pectoris (1); angiomas (1); angiosarcoma (1); Anorexia (1); Anxiety (1); anxiety disorder (1); asthma (1); atherosclerosis (1); atrial fibrillation (1); autism spectrum disorder (1); autoimmune disease (1); cardiac disease (1); cardiac hypertrophy (1); cardiovascular disease (1); cavernous angioma (1); cerebral palsy (1).
A further 35 diseases each share a sentence with KCNQ5 in 1 paper.